STAT1 (signal transducer and activator of transcription 1)
Diseases named in the same sentence as STAT1 in open-access papers (continued):
Sharing a sentence is not in itself a finding about the gene and the disease.
cancer (continued). "Our transcriptomic analyses of CM-treated HOSEs uncovered gene-expression profiles defining responses to cancer-like TME, highlighted by STAT1, ISG15, and OAS1 in HOSE1C and ITGA2, GREM1, and CDH13 in HOSE2C." (PMID 39634630, 2024). "In contrast, even though we did not determine the detailed mechanism, DRG2 depletion enhanced STAT1/IRF1 signaling pathway and the expression of PD-L1 in cancer cells after IFN-γ treatment." (PMID 38802348, 2024). "High IDO1 expression often co-segregated with high expression of immune checkpoints across cancers and there was an independent, statistically significant, and linear relationship between IDO1 expression and that of PD-L1, STAT1, and CXCL10 transcripts." (PMID 38632994, 2024). "Recent studies have reported STAT1 and STAT6 as regulators of proinflammatory and anti‐inflammatory microglial phenotypes in cancer." (PMID 39107960, 2024). "Next, the levels of STAT1 and phosphorylated STAT1 were evaluated, which revealed that IFN-γ induced STAT1 expression and phosphorylation augments were significantly reversed by CGA in these three cancer cell lines." (PMID 38164171, 2024). "We confirmed the activation of IFN‐I signaling in cancer cells with MSC‐DC, as reflected by increased phosphorylation of STAT1 and STAT2 and increased IRF9 expression, which was reduced by Gap26." (PMID 38638003, 2024). "Polyphenolic compounds primarily modulate PD-L1 expression by inhibiting key signaling pathways (IFN-γ-induced STAT1, STAT3, JAK2/STAT1, EGFR/Akt, and NF-κB), potentially enhancing the immune system’s capacity to target and eradicate cancer cells." (PMID 38594256, 2024). "Mechanistically, ID1 interacts with STAT1 to induce its cytoplasmic distribution and inhibits STAT1-mediated SerpinB2 and CCL4 transcription, two secretory factors responsible for cancer stemness inhibition and CD8+ T cell recruitment." (PMID 37996458, 2023). "AIM2, ZBP1, STAT1, and FAS mediate the immune response and play important roles in a variety of diseases, cancers, and infections." (PMID 37205113, 2023). "STAT1 and STAT3 are generally viewed as mediating opposite roles in cancer development, with STAT1 suppressing tumorigenesis and STAT3 promoting oncogenesis." (PMID 38022653, 2023). "In this review, we investigate the specific roles of STAT1 and STAT3 in normal physiology and cancer biology, explore their interactions with each other, and offer insights into therapeutic strategies through modulating their transcriptional activity." (PMID 38022653, 2023). "Among the STAT family proteins, STAT1 to STAT6, it was revealed that STAT3 functionally plays an important role in manipulating the biological activities of cancer cells, by affecting their energy metabolism, that is, the metabolism of glucose and lipids." (PMID 36899895, 2023). "We next conducted siRNA-mediated STAT1 knockdown experiments in murine MC38wt and human HCA-7 colony 29 cancer cells to further elucidate the mechanism of AIFN−γ-induced PD-L1 expression." (PMID 38102680, 2023). "The apoptotic effect of EGFR can also lead to biased signaling downstream by STAT1 and STAT3 activation in cancer cell lines." (PMID 37259433, 2023). "In specific, TIS is referred to as an 18‐gene signature (CCL5, GZMK, CD3D, CD3E, CD2, HLA‐DRA, IL2RG, NKG7, CIITA, CXCR6, LAG3, TAGAP, HLA‐E, CXCL13, IDO1, CXCL10, STAT1, and GZMB), which was related to the response to ICIs in various cancers." (PMID 37434432, 2023). "Nevertheless, several lines of evidence also link the cGAS-STING pathway, STAT1 activation and IFN signaling to the upregulation of the expression of the immune checkpoint protein PD-L1 in cancer cells as well in cells of the immune system." (PMID 36960066, 2023). "More importantly, it is clear that other STAT family members—STAT1, STAT2, STAT4, and STAT6—also contribute critical roles to cancer progression, either modulating the cancer cell directly or by altering cells of the TME." (PMID 37173951, 2023).
cancer (continued). "Certain signaling pathways were increased in cancer patient PBMCs (IL-10-induced p-STAT3 in helper T, Treg, and cytotoxic T cells) while others were decreased (IL-6 induced p-STAT1 in helper T, Treg, and cytotoxic T cells) compared to healthy control PBMCs." (PMID 37741983, 2023). "The major gene targets of four core herbs, MMP9, BCL2, STAT1, and STAT3, each as a subset of pathways in cancer, were confirmed to be involved in the MAPK pathway, the mTOR pathway, and cytokine–cytokine receptor interaction." (PMID 37631075, 2023). "The genes in Cluster-1, such as MCM2, STAT1, BRCA1, and MCM5, are overexpressed in the cancer samples." (PMID 37925498, 2023). "However, STAT1 could also act as a double-edged sword in inflammation and cancers." (PMID 35158821, 2022). "The gene of STAT genes was altered in 1,003 (9%) samples; STAT1, STAT2, STAT3, STAT4, STAT5A, STAT5B, andSTAT6 were altered in 2.3%, 1.7%, 2.0%, 2.4%, 1.6%, 1.9%, and 1.9% of the demanded pan-cancer samples." (PMID 36176415, 2022). "IL22RA1 was positively correlated with STAT1, STAT3, JAK1, PTPN11, IFNA13, IL24, but negatively correlated with IL10 in specific cancers." (PMID 35874683, 2022). "The cGAS/STING pathway is a major regulator of DDRi-induced immune stimulation, though the STAT1 pathway, TRAIL pathway, and direct activation of anti-cancer immune cells also play important roles." (PMID 36276148, 2022). "We therefore set out to quantify to what extent the PD-L1 mRNA level (CD274) in cancer patients can be predicted by activity of the relevant TFs MYC, HIF1A/2A, JUN, IRF1, STAT1/3, NFKB, and NRF2." (PMID 35289334, 2022). "IFN-γ-induced PD-L1 expression has been reported in several cancer cells, and this mechanism is mostly mediated by activating IFNGR1/2-Janus kinase (JAK)/STAT1 pathways." (PMID 35269423, 2022). "In previous reports, ZMYM2-FGFR1 continuously activates the kinase domain in the C-terminal and FGFR signalling, resulting in STAT1/3 phosphorylation and the induction of diverse genes involved in cell survival and proliferation by ERK1/2 in cancer cells." (PMID 35013300, 2022). "In LUAD, miR-944 directly targets and inhibits STAT1 expression, inhibits the activation of the Jak/STAT signaling pathway, thereby inhibiting cancer cell proliferation, and also hinders tumor growth in BALB/c nude mice." (PMID 36077769, 2022). "The results showed that in OVA expressing cancer cells, DENR depletion resulted in weaker p-STAT1 signaling, lower PD-L1 expression, and significant higher percentage of apoptotic cells." (PMID 35440133, 2022). "It is important to differentiate STAT1 and STAT2 from other STAT family members such as STAT3 and STAT5, which contribute to cancer cell survival, proliferation, and angiogenesis." (PMID 36276148, 2022). "Several transcription factors, such as STAT1/3, HIF-1α, NF-κB, AP1, and MYC, and various cytokines, including IFN-γ, and TGF-β, have been shown to regulate the expression of the PD-L1 gene in cancer cells." (PMID 35626102, 2022). "In conclusion, we found IRF1 to be a general predictor for CD274 expression in all three studied cancer types, and STAT1, NFKB, HIF1A and BRD4 to be predictors for some of these cancer types." (PMID 35289334, 2022). "miR-155 overexpression in cancer cells enhances immune cell influx by increasing the production of chemoattractants via suppressing SOCS1 and tilting the p-STAT1/p-STAT3 balance." (PMID 35925680, 2022). "Signal transducer and activator of transcription 1 (STAT1) is a transcription factor that responds to interferons and is universally expressed in a variety of cell types, including cancer cells." (PMID 35606369, 2022). "The excellent extrapolation of this generalized model to other cancer types for which fewer data are available provides confidence that the TFs IRF1, STAT1, NFKB, and BRD4 are in general dominant regulators of CD274 expression." (PMID 35289334, 2022).
cancer (continued). "We inferred that LSECtin can also regulate STAT family members STAT1, STAT3, and STAT5A, which have been reported to be closely related with cancer." (PMID 35821222, 2022). "Research has shown that abnormalities in 12 signaling pathways mainly relate to the occurrence and development of cancer, with the JAK/STAT1 signaling pathway being one of these pathways." (PMID 35692770, 2022). "Most of the activated TFs are involved in cancer progression through the TIME, such as the NFκB family (NFKB1, NFKBIA, and RELA) and the STAT family (STAT1, STAT2, and STAT6), which are critical in M1 and M2 macrophage polarization." (PMID 36230879, 2022). "Cancer cells are known to secrete cytokines, including interferons, which in an autocrine manner can regulate the constitutive IDO1 expression via the JAK1/STAT1 signaling pathway." (PMID 35997090, 2022). "Along with STAT2, STAT1 induces IFN-regulated genes, enhances antigen presentation, and contributes to an inflammatory, anti-cancer response." (PMID 36276148, 2022). "In carcinomas, constitutive STAT3 activation also reduces the expression of ISGF3 components (such as IRF9, STAT1, and STAT2) and IRF7, a transcription factor that participates in IFN response-related gene expression by directly binding to gene promoters." (PMID 36358904, 2022). "More directly, our findings provided evidence that the expression of DKK1 was correlated with the level of Th1 markers (STAT1 and IFNG) and Th2 markers (GATA3 and STAT6) in various cancers, such as ACC, KICH, MESO, and PAAD." (PMID 34899842, 2021). "The major oncogenic actions of TYK2 are mediated through STAT1, STAT3, and STAT5, and drugs targeting STATs are in development for cancer therapeutics." (PMID 34439323, 2021). "ESR1, TOR1AIP1, STAT1, COL1A1 were identified as high expression, while EGFR, AR, GATA2 were identified as a low expression in both cancer types." (PMID 33907495, 2021). "The IFN/STAT1 pathway modulates the expression of classical IFN-regulated genes that have key immune effector functions and play crucial roles in the efficacy of cancer immunotherapies." (PMID 34771447, 2021). "In this study, we investigate how an intracellular signalling network (STAT1, STAT3, Bcl-2 and BAX) regulates important cellular states, either anti-apoptosis or apoptosis of cancer cells." (PMID 34631119, 2021). "Bi-stable regulation of the STAT1 and STAT3 can induce a phenotypic onset that promotes or suppresses cancer progression." (PMID 34631119, 2021). "The results showed that oncoVV-WCL downregulated the activity of ISRE and led to STAT1 cleavage, suggesting that oncoVV-WCL regulated the antiviral response in cancer cells through STAT1 cleavage." (PMID 34064193, 2021). "The dual inhibition of STAT1 and STAT3 activation downregulates the expression of PD-L1 in cancer cells." (PMID 34827136, 2021). "(ii) In breast cancer, IRDS expression measured suggests seven genes (STAT1; MX1; ISG15; OAS1; IFIT1; IFIT3; and IFI44, interferon induced protein 44) whose cancers are resistant to therapies." (PMID 33922087, 2021). "Relative balance between STAT1 and STAT3 levels in cancer cells determines two different dichotomous states: (i) an apoptosis progression and (ii) an anti-apoptosis state (inactivation of cell death program)." (PMID 34631119, 2021). "In solid cancers, STAT1 and STAT3 have pleiotropic roles during cancer development and in the establishment of immune responses." (PMID 33807608, 2021). "Some of the other enriched transcription factors include MYB, BRCA1, STAT1 and ETV4 which are upregulated in majority of the cancer types." (PMID 34728699, 2021). "PLSCR1 was enriched in the promoter region of STAT1 and enhanced STAT3 binding to the STAT1 promoter, resulting in transactivation of STAT1; STAT1 then enhanced cancer stem cell (CSC)-like properties that promoted BLBC progression." (PMID 32292520, 2020).
cancer (continued). "In contrast, HER2-low cancers showed differential response to IFN-β, even though STAT1 phosphorylation by IFN was observed." (PMID 33505314, 2020). "Recent work indicated that EIF4F affects translation of the signal transducer and activator of transcription 1 (STAT1) protein, which leads to the overexpression of PD-L1 on the surface of cancer cells." (PMID 32483460, 2020). "At the molecular level, monensin has pleiotropic effects affecting multiple cancer-related pathways such as the E2F/DP1, STAT1/2, NFκB, AP-1, Wnt, and Elk-1/SRF pathways, likely dependent on the cellular model." (PMID 32093282, 2020). "Three of these proteins—STAT1, STAT3, and STAT5—have been reported to be involved in cancer development." (PMID 33003453, 2020). "STAT1 is known to play a prominent role as an activator of the antitumor immune response, while STAT3 and STAT5 are primarily involved in promoting cancer progression." (PMID 33003453, 2020). "Inversed correlation between p-Stat1 and cyclin D1 was observed in ESCC cancer tissues with IHC staining." (PMID 33046973, 2020). "Previous studies have shown that transcription factors such as c-Jun, c-Fos, STAT1/3, S6K and IRF are involved in PD-L1 expression in cancer cells." (PMID 32024543, 2020). "We further examined the expression of SOCS1 and STAT1 proteins in NPC tumors and para-carcinoma tissues by IHC." (PMID 32831137, 2020). "Our results showed STAT1 levels were higher in cancer tissues #3 and #4S, while STAT3 levels were higher in cancer tissues #3, #4, and #5, but the correlation with CFH expression was weaker than that of STAT4." (PMID 30987235, 2019). "It has been demonstrated that microRNA-146a can target many genes, such as IRAK1, IRAK2, TRAF6, RIG-I, IRF-5, STAT-1, PTC1, Numb, and WASF2, to play a variety of roles in human diseases, including cancers and inflammatory immune diseases." (PMID 31798643, 2019). "In interferon-γ-treated cancer cells, cytoplasmic HSP90α acts as a chaperone protecting JAK1/2 from degradation and thus enhances STAT-1 phosphorylation and the downstream gene expressions." (PMID 31847880, 2019). "Recently, several studies have shown that various transcriptional factors, such as STAT1, STAT3, BRD4, NF-kB, PI3K/AKT/mTOR, and MEK1/2/ERK1/2, promoted PD-L1 transcription in cancer cells." (PMID 31818309, 2019). "Here, STAT1, the first member of signal transducer and activator of transcription (STAT) family, has been involved in cancer suppression, including CRC." (PMID 31214045, 2019). "Stat1 is transferred to pStat1 by JAK phosphorylation, and the overexpression of the Stat1/INF pathway has been recently reported to be related with the resistance of chemotherapy and radiotherapy, metastasis, and poor prognosis in malignant tumors." (PMID 30174790, 2018). "Our data unveil a novel insight into the molecular mechanism of crosstalk between the STAT1 and TGF-β signaling pathways, which affected the cancer cell behavior." (PMID 29751820, 2018). "Stimulation with IFN-γ, TLR ligands and LPS via MyD88, TRAF6, MEK, STAT1, NF-κB and PI3K-dependent pathways increased PD-L1 expression in different types of cells, such as inflammatory cells, fibroblasts and cancer cells." (PMID 29690901, 2018). "In this study, we also investigated the effect of monensin on multiple cancer-related pathways and found that monensin can inhibit E2F/DP1, STAT1/2, NFκB, AP-1 and Elk-1/SRF pathways." (PMID 30559409, 2018). "Cancer cells can upregulate the expression of SOCS1 and SOCS3 proteins which leads to a decline in IFN-induced STAT1 phosphorylation." (PMID 30186768, 2018). "Signal transducer and activator of transcription 1 (STAT1) is a member of the STAT protein family, which plays important roles in cancer inflammation." (PMID 29796115, 2018). "Specifically, EGCG differently regulates the levels of STAT1, STAT3 and Bcl-xL proteins in normal cochlear and cancer cells." (PMID 28703809, 2017).
cancer (continued). "Altogether, this data describes a complex relationship between STAT1 and STAT3 signaling in cancer that should be considered when developing STAT-targeting compounds." (PMID 28636670, 2017). "The activated JAK1 and TYK2 in turn phosphorylate STAT1 and STAT2 setting in motion a cascade of events which finally initiates the transcription of IFN-inducible genes switching on the anti-cancer and anti-viral effects as reviewed in Randall and Goodbourn." (PMID 28344639, 2017). "In cancer, EGFR has been shown to have growth inhibitory effects as it induced the expression of IRF-1 via phosphorylation of STAT1 and STAT3." (PMID 26881744, 2016). "This study provides the first evidence that chemotherapy used at sub-lethal doses can trigger the STING/IFN pathway in some cancer cells, which in turn contributes to survival to treatment via specific IFN/STAT1 target genes." (PMID 27791205, 2016). "There are seven members in STAT family; in particular, STAT1 and STAT3 play important roles in cancer cells." (PMID 26909593, 2016). "The specific inhibition of STAT3 is important for treating cancer cells because certain growth suppressive cytokines, such as IFN-γ, activates STAT1, which mediates growth suppressive signals, as well as STAT3, which promotes cell growth." (PMID 26010889, 2015). "Normal intestinal fibroblasts activate signal transducer and activator of transcription 1 (STAT1) signaling in CRC cells and in contrast to CAFs, inhibit growth of cancer cells." (PMID 25853091, 2015). "The malignant tumors displayed a significantly higher module score than the benign and borderline tumors for the AURKA/proliferation, STAT1/immune response, CASP3/apoptosis, VEGF/angiogenesis and ERBb2/HER2 signaling modules." (PMID 25226589, 2014). "The expression level of six differentially expressed mRNAs (CUL2, HIF1A, RET, JAK1, STAT1, and BCL2) in the cancer pathway and two of their nearby lncRNA pairs (RP11-124O11.2 and lincRNA-TMEM30B-1) was verified by real-time quantitative RT-PCR (qRT-PCR)." (PMID 24672800, 2014). "The mean expression of all the STATs and phospho-STATs, with the exception of phospho-STAT1(Tyr701) expression (and total STAT3 in the cytoplasm), were enhanced in their respective nodes relative to expression in the primary cancer." (PMID 24728078, 2014). "In contrast with STAT1, STAT3 promotes survival, proliferation and motility of cancer cells, and induces immune tolerance." (PMID 25355139, 2014). "We find significant evidence of the OVOL, AP1, STAT1, STAT3, and NFKB1 TFs having important roles in MET, and more broadly in cancer." (PMID 24612742, 2014). "For this gene set, we found significant enrichment of annotation for BC, PC, cancer, and MET, as well as regulation of gene expression by AP1, STAT1, STAT3, and NFKB1." (PMID 24612742, 2014). "Taken together, we propose that engagement of immune cells and cancer cells by trastuzumab triggers the release of IFN-γ, which activates STAT1-mediated transcriptional downregulation of HER2 in cancer cells." (PMID 24693969, 2014). "To further mechanistically confirm the link between STAT1 and IDO expression, we silenced STAT1 in the MDA-231 cancer cell line by siRNA." (PMID 24911872, 2014). "The relationship between IL-6 and IFN-γ is striking given the often distinct roles of STAT1 and STAT3 in inflammation and cancer." (PMID 24412616, 2014). "Addition of fludarabine, an inhibitor of STAT1, reduced levels of both pSTAT1 and total STAT1 and blocked HER2 downregulation in cancer cells cultured with the CM from the co-treatment with PBMCs and trastuzumab." (PMID 24693969, 2014). "IFN-α and IFN-γ enhance TRAIL expression via a STAT1– and IRF-1–dependent mechanism in cancer cells." (PMID 24155891, 2013). "On this basis and given the fact that IL-27 regulates STAT transcriptional factors (STAT1 and STAT3) that possess opposing activities in cancer, the impact of this cytokine on lung carcinogenesis was investigated." (PMID 24274066, 2013).